EGFR (epidermal growth factor receptor)
Diseases named in the same sentence as EGFR in open-access papers (continued):
Sharing a sentence is not in itself a finding about the gene and the disease.
tumor (continued). "Therefore, in order to perfect the anti-tumor activity of c-Met targeted therapy and develop its function in treating drug-resistant tumors, future studies should further explore the interaction mechanism between c-Met and EGFR." (PMID 35978812, 2022). "Most effects of microglia on tumor cell migration and motility were associated with secreted soluble factors, such as transforming growth factor-beta (TGF)-β, epidermal growth factor receptor (EGFR) ligands, diverse interleukins, and matrix metalloproteinases (MMP)." (PMID 35011711, 2022). "Moreover, in vitro studies have shown that EGFR mutation-positive NSCLC can change its non-inflammatory tumor microenvironment and improve its responsiveness to PD1 inhibitors after intervention." (PMID 36185620, 2022). "Consequently, systemically delivered oAd/DCN-shMet/PPE showed a 14.9-fold higher level of tumor growth inhibition in an EGFR-positive orthotopic lung tumor model in comparison with naked Ad, ultimately resulting in complete tumor regression in 66% of the treated mice." (PMID 35444290, 2022). "Moreover, though mouse and human EGFR sequences are quite conservative, they do differ, so that some EGFR-targeted agents possess specificity only to human EGFR, requiring the use of a tumor model expressing human EGFR." (PMID 36432639, 2022). "When using 36.3% as the optimal cut-off point for EGFR(+), 11/12 (91.7%) cases of EGFR mutation-positive tumor samples showed positive for the ratio of EGFR(+), and 9/11 (81.8 %) cases of these EGFR mutation-negative tumor tissues were negative for the ratio of EGFR(+)." (PMID 36376325, 2022). "In addition, the nuclear localization of EGFR is closely related to tumor resistance." (PMID 35152831, 2022). "The poor survival benefit of anti‐EGFR therapy in the right‐sided tumor group may result in a small prognostic benefit, and as a result, the antitumor effect of the increase in the number of drugs administered on the OS of patients with right‐sided tumors was poor." (PMID 35182029, 2022). "Furthermore, as a predictive effect of tumor sidedness, chemotherapy plus anti-epidermal growth factor receptor (EGFR) antibody compared with chemotherapy alone or chemotherapy plus bevacizumab had a great effect, with the effect being greatest in patients with left-sided tumors." (PMID 35565247, 2022). "Therefore, blockade of EGFR signaling by either small-molecule inhibitors or anti-EGFR monoclonal antibodies may not only inhibit tumor growth but also exacerbate cachexia symptoms in clinical settings." (PMID 36471329, 2022). "Additionally, the humanized anti-EGFR cetuximab in conjunction with immune checkpoint blockers such as anti-NKG2A antibody (monalizumab) can dramatically improve NK cell anti-tumor activity against glioma cells, notably in individuals resistant to temozolomide." (PMID 36305981, 2022). "First, although our NMA suggests that first-generation EGFR-TKIs plus chemotherapy is the most favorable strategy for non-elderly advanced EGFR-mutated NSCLC patients, no RCTs have compared the efficacy of combing second or third generation EGFR-TKIs and chemotherapy to other anti-tumor treatments." (PMID 35525919, 2022). "PD-1 and PD-L1 inhibitors are the mainstay of systemic treatment for aNSCLC in patients without therapeutically actionable tumor genomic aberrations, such as epidermal growth factor receptor (EGFR) mutations, anaplastic lymphoma kinase (ALK) translocations or ROS proto-oncogene 1 (ROS1) fusions." (PMID 36008722, 2022). "MEK/Erk and PI3K/Akt could also be activated by different growth factors, such as EGFR and ErbB3, thus tumor types and stages, as well as CD44 isoforms and expression levels should be considered when these inhibitors are combined with chemotherapy for PDAC treatment." (PMID 35931675, 2022).
tumor (continued). "In addition, 51 shows a considerable selectivity profile for c-Met over other kinases (FLT3, VEGFR2 and EGFR) and exerts significant inhibitory activities against diverse types of tumor cells through arresting the cell cycle in the G2/M-phase inducing cell apoptosis." (PMID 35799213, 2022). "As expected, tumor sample #15-T was negative for both EGFR mutation-specific antibodies." (PMID 36376325, 2022). "Simple tests, such as detecting only actionable mutations, e.g. EGFR exon mutations, may be further developed for not yet used genes, for example, rare and tumor-specific CD44v variant exon combinations." (PMID 39697490, 2022). "No other EGFR mutation was detected in the tumor tissue by PCR or NGS." (PMID 36551569, 2022). "Currently, various monoclonal antibodies targeting either EGFR, including the therapeutic antibodies panitumumab, necitumumab, nimotuzumab and cetuximab, or PD-L1, among them durvalumab, avelumab and atezolizumab are approved for tumor treatment in multiple countries." (PMID 35479092, 2022). "This was independent of the KRAS/BRAF mutation status and EGFR expression levels of tumor cells, thus suggesting that resistance mechanisms observed with the therapeutic agents targeting EGFR activity and signaling may not be relevant in this setting." (PMID 36185288, 2022). "Hence, studying the “ON/OFF” of the major tumor-driving EGFR/K-RAS/MAPK/SIAH pathway may represent an opportunity to risk-stratify TNBC patients before and after NACT/NST (IO-therapy)." (PMID 36176751, 2022). "However, it is unknown whether CSP-mediated inhibition of autophagy could improve the anti-tumor effect of EGFR-TKIs." (PMID 35186935, 2022). "In addition, for all of the tumours tested, aerotaxis seem to follow the cell signalling pathway initially described for untransformed breast cell lines, i.e. the oxygen-dependent redox regulation of EGFR." (PMID 36380366, 2022). "Although the biggest contribution to the therapeutic effect of amivantamab is likely due to EGFR inhibition, it is reasonable to speculate that synergistic targeting of MET must be a factor to help offer better tumor selectivity and avoid major toxicity resulting from WT EGFR inhibition." (PMID 34913823, 2022). "Circulating tumor DNA (ctDNA) in plasma samples can be an alternative method to detect EGFR mutations, but the results do not always agree with those of biopsy samples due to tumor heterogeneity, the false-negative rate is relatively high, and the cost is very high." (PMID 35422977, 2022). "The augmented anti-tumour effects could be due to the efficient cellular uptake of the siRNA/NPs complexes and the early release of the siRNA from the endosome, thereby silencing the expression of EGFR genes and inducing the apoptosis in the treated cells." (PMID 36412852, 2022). "Accordingly, inhibition of the epidermal growth factor receptor (EGFR) via gefitinib in AOM/DSS mice led to decreased tumour burden, and this correlated with a reduction in intestinal epithelial cell Il33 expression which the authors attributed to for the pro-tumoral effect of EGFR signalling." (PMID 36263033, 2022). "Recently, studying reports suggest that BRAF non-V600E tumours may be sensitive to EGFR inhibitors." (PMID 36819812, 2022). "Tumor cells often develop acquired resistance to ALK inhibitors, resulting from secondary mutations in the patient’s kinase domain, gene amplification, and activation of alternative signaling pathways (e.g., EGFR, kit, IGF1R, etc.)and epithelial mesenchymal transformation." (PMID 35620280, 2022). "Therefore, before EGFR-TKIs are taken by patients with NSCLC, it is necessary to determine whether the tumor tissue harbors gene mutations and identify the type of mutation in the EGFR gene." (PMID 36468116, 2022). "Moreover, there is evidence that EGFR mutations facilitate infections even of tumor cells without activated RAS." (PMID 35004328, 2021).
tumor (continued). "Integrins are important cell surface receptors that interact with their ligands in the tumor microenvironment; at times, they may cooperate with growth factor receptors, such as epidermal growth factor receptor (EGFR) signaling, to accurately transduce environmental cues into the cells." (PMID 33807786, 2021). "Similarly, SEPET could determine whether the tumor was EGFR mutant or wild-type based on the pattern of suspicious area with high or low FDG uptake." (PMID 34367993, 2021). "In addition, data on response evaluation, PFS, AEs, EGFR mutation type, and tumor involvement were not reported, which are the major limitations of retrospective cohort studies performed using data from the Cancer Registry databank." (PMID 34315431, 2021). "Moreover, the EGFR/AKT signaling pathway is closely related to tumor angiogenesis." (PMID 34294040, 2021). "In addition, CXCL14 expression is inversely correlated with EGFR expression in tumor cells." (PMID 34696665, 2021). "EGFR mutation-positive caused lack of TILs, impaired the antigen specific signal, made tumor cells unrecognizable to T cells, reduced programmed death receptor ligand-1 (PD-L1) expression, lower tumor mutation burden (TMB)." (PMID 34917497, 2021). "Furthermore, no significant weight loss was observed in the mice during treatment period, suggesting that cetuximab, ramucirumab or anti-EGFR/VEGFR2 BsAb treatment did not cause any systemic toxicity in tumor-bearing mice." (PMID 33804477, 2021). "Thus, inhibition of GABARAPL1 could potentially alter tumour growth by affecting intrinsic factors, for example, downstream signalling of EGFR, leading to decreased cell proliferation, resulting in decreased tumour growth." (PMID 34859607, 2021). "Internalization of inactive EGFR and diversion of ligand-activated EGFR from the lysosomal-degradation pathway resulting in their arrest at recycling endosomes might be particularly deleterious to tumor cells that crucially depend on EGFR function." (PMID 34298835, 2021). "Chi-squared tests showed that the high expression of PD-L1 (tumor proportion score [TPS] of ≥ 50%) was more common in male patients, smokers, the histological type of SCC and other in NSCLC, pathological stage II and IIIA, the presence of adjuvant therapy, and wild-type EGFR mutation status." (PMID 34471191, 2021). "However, a recently updated meta-analysis indicated that anti-EGFR therapies could remain an option for patients with RAS wildtype right-sided tumours, as this significantly improved PFS and therapy response in both left- and right-sided tumours." (PMID 34253874, 2021). "Therefore, we speculate that higher PD-L1 expression in NSCLC patients may lead to EGFR-TKI resistance through tumor microenvironment and eventually result in a poor prognosis for TKI treatment." (PMID 33964931, 2021). "Furthermore, AT1R enhances the tumorigenic and proliferative effects of EGFR, which may be part of its recently discussed role in tumour biology." (PMID 34921637, 2021). "The observed OS difference may therefore be attributed to the more pronounced tumour response, reflected by the depth-of-response data, in combination with the more favourable treatment sequence of anti-EGFR treatment followed by anti-VEGF than the other way round." (PMID 33154570, 2021). "Therefore, iNPs could effectively deliver and extensively accumulate EGFR-targeted drugs in tumor tissue, reducing the accumulation of drugs in normal tissues." (PMID 34322025, 2021). "Interestingly, EGFR wild type that was enriched in the IFNGrGS score-high group may be related to the immaturity of the vascular system, tumor tissue hypoxia, and necrosis." (PMID 34566988, 2021).
tumor (continued). "Additionally, GR-positive non-tumor liver tissues displayed lower EGFR expression." (PMID 33806040, 2021). "In this study, we found that serum CEA and tumor grade were potentially associated with uncommon EGFR mutation, whereas no significant correspondence was found in stage and ECOG PS, which had been proved to have independent prognostic value for NSCLC patients in previous studies." (PMID 34976788, 2021). "Furthermore, microbial metabolites, such as polyamines and secondary bile acids, are also involved in cancer cell proliferation and tumor induction through the β-catenin signaling pathway, epidermal growth factor receptor (EGFR) transactivation, and increased COX-2 activity." (PMID 34199351, 2021). "Given that HDAC1 overexpression and EGFR activity are strongly related with tumor progression and cancer cell survival, HDAC1 tyrosine phosphorylation may present a possible target to manipulate HDAC1 protein levels in future potential cancer treatment strategies." (PMID 33976119, 2021). "After EGFR binds to ligands, both extracellular and intracellular domains of receptor tyrosine kinase undergo dynamic conformational changes, resulting in common phenotypes in tumor cells, such as cell evasion of apoptosis, proliferation, invasion, and metastasis." (PMID 33190424, 2021). "Overall survival in these mice was increased further when they were treated with the epidermal growth factor receptor (EGFR) tyrosine kinase inhibitor, erlotinib, indicating that this adjunct therapy may be effective at overcoming EGFR inhibitor tumour resistance." (PMID 35047989, 2021). "Moreover, only osimertinib/trametinib combination treatment, but not monotherapy with either of these drugs, leads to robust tumor shrinkage in EGFR-driven xenograft models harboring BRAFV600E mutations." (PMID 34921211, 2021). "Therefore, EGFR is an attractive target for tumor imaging and therapy." (PMID 33809064, 2021). "Furthermore, accumulating evidence suggests that multiple components of EGFRm tumor biology may predict response to ICI therapy, including specific EGFR mutation, TMB, PD-L1 expression, and TIL density among others." (PMID 34868953, 2021). "Interestingly, a higher ALKBH4 expression was detected in tumour tissues than in matched-pair normal tissues, regardless of the presence or absence of epidermal growth factor receptor (EGFR) gene mutations." (PMID 33883577, 2021). "Additionally, follow up studies reported that cetuximab responders exhibited upregulation of CD137, a marker of NK cell activation, on tumor infiltrating NK cells and an increase in frequency of circulating EGFR-specific T cells between cetuximab-treated and cetuximab-naive patients." (PMID 33485341, 2021). "EGFR and PUMA seem to have a high co-expression in cell lines and primary specimens of different types of tumor cells, suggesting that EGFR overexpression might have anti-apoptotic and therefore oncogenic activity, even without the involvement of its kinase-dependent intracellular pathways." (PMID 33451055, 2021). "Moreover, our strategy to generate in vivo SR models via chronic anti-EGFR treatment was able to successfully mimic the parallel evolution of multiple resistant lesions per patient tumor, represented in our setting by the multiple SR tumors evolving in the majority of our tested PDX models." (PMID 34271981, 2021). "However, since our genetic analyses in C. elegans indicated that negative regulation of RAS-MAPK signaling by LRIG/SMA-10 required the presence of EGFR/LET-23, we hypothesized that a tumor-suppressive function of LRIG1 may be exerted at the EGFR level." (PMID 33947959, 2021). "Four optimal features were selected to predict EGFR mutation status, Tumor-Mass, Sigmoid-Offset-Mean, Gabor-Energy and DWT-Energy, which quantified tumor mass, tumor-parenchyma density transition at boundary, line-like pattern inside tumor and intratumoral heterogeneity, respectively." (PMID 33681463, 2021).
tumor (continued). "The findings of the present MPLC study confirms that some cases with EGFR- or KRAS- mutated tumours are strongly related to non-intrinsic factors and suggests that the other most mutations may occur by chance." (PMID 33707471, 2021). "The tumor genotyping of five other patients showed a wild‐type EGFR gene, and these negative results could be linked to a low amount of tumor DNA, pre‐ or post‐analytic error, or spatial heterogeneity of the tumor." (PMID 33270375, 2021). "Furthermore, anti-VEGF and anti-EGFR can also affect tumor microenvironment (TME)." (PMID 34109130, 2021). "We first examined whether EGFR coordinates with CD44 in tumor clustering." (PMID 33995681, 2021). "In a tumor study, EGFR C797S frequency was higher for 29% of cases and was preferentially coupled with EGFR exon 19 deletion compared to L858R (24% versus 11%), and was only seen in tumors that retained T790M, suggesting continued EGFR dependance in these tumors." (PMID 34638411, 2021). "Therefore, a greater structural understanding of receptor activation in EGFR-mutant tumours may yield biomarkers for mAb combination therapy in cases of acquired resistance." (PMID 34069119, 2021). "Two main questions were posed by the study: (i) whether high EGFR expression is sufficient to transform adhesive MCF7 cells to 3D culture, and (ii) how the transformation into spheroids changes cellular markers associated with tumor progression and drug resistance in MCF7-EGFR spheroids." (PMID 34884742, 2021). "In NSCLC, mutation or overexpression of EGFR promotes immunosuppression, and the inhibition of EGFR using gefitinib or erlotinib can restore MHC class I expression, reduce PD-L1 expression or upregulate the expression of NKG2D ligands for NK cell-mediated tumor killing." (PMID 33807608, 2021). "A clear example is given by [11C]erlotinib, where both SUV and TBR, derived from static scans, do not show significant differences between tumours with and tumours without mutated epidermal growth factor receptors (EGFR), in contrast to the volume of distribution (VT) derived from dynamic scans." (PMID 34136956, 2021). "The four radiomics features model, built using a Random Forest algorithm to diagnose anti-EGFR treatment-sensitive tumors, outperformed both KRAS-mutational status at baseline (AUC = 0.67, p < 0.001) and 8-week tumor shrinkage (RECIST 1.1-like unidimensional tumor shrinkage)." (PMID 33652647, 2021). "Considering that it is difficult to detect ≤ 1% mutant DNA using conventional PCR, ultrasensitive ddPCR is necessary to detect EGFR mutations in the tumor cells in sputum, because of the abundant normal cells or non-mutated DNA in the background of a sputum sample." (PMID 33757469, 2021). "Besides, a prominently higher tumor T status was found in subjects with LncRNA H19 SNP rs2107425 T allele (CT + TT) (stage III or IV, p = 0.007) compared to EGFR wild-type LADC individuals with LncRNA CC allele in EGFR wild-type patients." (PMID 33799753, 2021). "However, the modulation of EGFR and the associated signaling pathways by features of the tumor microenvironment, in particular by hypoxia, has not been investigated systematically." (PMID 33718186, 2021). "Researchers advised that for patients who harbored a high ratio of EGFR mutation in tumor, EGFR-TKI was effective to control the progression of tumor, but for the low, monotherapy of EGFR-TKIs may be not enough." (PMID 34692766, 2021). "Based on our hypothesis, maximum tumor growth reduction by targeted SA-5-Dox-LP formulation could be due to a combined effect of EGFR heterodimerization inhibitory action by SA-5 and maximized the activity of functionalized Dox liposome formulation due to its EPR effect." (PMID 33800723, 2021).